IGF1R (insulin like growth factor 1 receptor)
Diseases named in the same sentence as IGF1R in open-access papers (continued):
Sharing a sentence is not in itself a finding about the gene and the disease.
myeloma (continued). "In human multiple myeloma cell lines, IGF1 induced proliferation and antiapoptotic effects via IRS1-dependent PI3K/AKT and MAPK activation, even in IL6-independent cell lines, indicating that the IGF1R/IRS1 axis plays an important role in the development and progression of this disease." (PMID 30328953, 2018). "The combination of the anti IGF-1R antibody with AS602868 increased the cytotoxic effect in MM cell lines, suggesting that simultaneous targeting of IGF-1 signalling and the NF-κB pathway could be of therapeutic value in multiple myeloma." (PMID 21799925, 2011). "Also unique to the myeloma cells compared to carcinoma or endothelial cells is that IGF-1R in the pre-assembled Sdc1-coupled ternary receptor complex is constitutively active; it is not dependent on cell adhesion or IGF-1, although exogenous IGF1 stimulates increased levels of IGF-1R activation." (PMID 34778093, 2021). "The signaling pathway downstream of IGF-1R that activates talin and thus the αvβ3 or αvβ5 integrin remains to be identified and the question remains as to whether it is present but inactive in myeloma cells, or if a critical component of the pathway is lacking altogether." (PMID 34778093, 2021).
Obesity (52 papers, 2009 to 2025). Accumulation of substantial excess body fat. "We also found that endothelial IGF-1R knockdown in the setting of obesity increased eWAT vascularity, which was associated with increased ex vivo sprouting and Vegfa gene expression." (PMID 39747815, 2025). "(2012) which shows that fat specific IGF1R and insulin receptor double knock out mice were resistant to age-associated and diet-induced obesity and glucose intolerance." (PMID 36353242, 2022). "The receptor for leptin, an obesity-associated adipokine that was significantly elevated in our obese patient group, has also been shown to crosstalk with IGF-1R, resulting in greater IGF-1R activation and an upregulation of Akt and ERK1/2 phosphorylation." (PMID 23880059, 2013). "Moreover, the downregulation of miR-320a participates in regulating multiple signaling pathways, including PI3K/AKT and MAPK/ERK, by targeting IGF-1R, which is associated with obesity and T2D." (PMID 35534828, 2022). "However, the underlying molecular links among DLK1, IGF1/IGF1R signaling pathway, and miRNA-379/miR-544 cluster in obesity-mediated metabolic dysfunction, like NAFLD, are mostly poorly understood." (PMID 34527673, 2021). "Here, we explored the role of endothelial IGF-1R as a paracrine modulator in the pathophysiology of obesity." (PMID 39747815, 2025). "It is strongly associated with HS, among other dermatoses, as evidenced by the dysregulated expression of proteins related to metabolism/obesity (PPARγ, IGF-1R, and irisin)." (PMID 40869025, 2025). "Estrogen also amplifies mTOR outputs via IGF-1R upregulation, sustaining proliferative/survival programs that are accentuated in obesity-related endocrine milieus (increased aromatization, reduced SHBG)." (PMID 41301707, 2025). "We used a murine model of high-fat feeding with endothelial-specific IGF-1R knockdown to examine the role of this evolutionarily preserved transmembrane receptor in endothelial cells in response to nutritional obesity." (PMID 39747815, 2025). "Our in silico analysis highlighted the IGF1R signaling pathway as a key enriched mechanism, linking selected ncRNAs with metabolic dysregulation and inflammation in obesity-related asthma." (PMID 41156032, 2025). "We show that IGF‐1R facilitates crosstalk between the EC and the gut wall; this crosstalk protects against diet‐induced obesity, as a result of an altered gut microbiota." (PMID 33934497, 2021). "Our study showed that upregulation of the IGF1/IGF1R signaling pathway protected the miR-379/miR-544 cluster KO mice against high-fat diet-induced obesity." (PMID 34527673, 2021). "Here, we identified miR-379/miR-544 cluster as the critical regulator to resist HFD-induced obesity and regulate moderate hepatic steatosis via targeting Igf1r and Dlk1 directly." (PMID 34527673, 2021). "Here, endothelial specific over‐expression of IGF‐1R is shown to promote advantageous remodelling of the gut microbiota upon high fat diet, which protects against the development of obesity." (PMID 33934497, 2021). "Secondly, no normal-weight children were analysed, making it difficult to deduce the potential relevance of IGF1R-aAb for obesity." (PMID 31940750, 2020). "We have provided a number of insights into changes in the IR/IGF-1R/hybrid receptor system as obesity progresses, showing that after long-term obesity, IGF-1-mediated Akt phosphorylation is preserved in aorta and resistance vessels." (PMID 30295509, 2019). "Among RTKs, IGF-1R is thought to be one of the most critical targets for the inhibition of obesity-related carcinogenesis by tea catechins, although the direct alteration of catechins on IGF-1R needs to be clarified." (PMID 28445390, 2017). "The findings of these studies suggest that the molecular consequence of obesity is the increased expression of IGF-1R in both normal and malignant tissue." (PMID 21696633, 2011).
Obesity (continued). "Here the authors show that lowering IGF-1R levels in endothelial cells improves insulin sensitivity, boosts energy use, and supports beneficial changes in adipose tissue, offering insights into potential treatments for obesity-related metabolic disorders." (PMID 39747815, 2025). "IGF1R plays an important role in metabolic homeostasis, and its effects may vary depending on factors such as diet-induced obesity and aging." (PMID 40864762, 2025). "Interestingly, IGF1R, a receptor tyrosine kinase that mediates actions of insulin-like growth factor 1 and one of the factors that are altered in obesity is a key target of differentially expressed miRNAs identified by our framework including miR-182-5p." (PMID 35937842, 2022). "Therefore, to explore the effects of endothelial IGF‐1R on metabolic responses to obesity and the microbiome, we fed mice with endothelial cell overexpression of human IGF‐1R (hIGFREO) an obesogenic high‐fat high‐calorie diet." (PMID 33934497, 2021). "The NF-κB target genes JUN, PIK3R1, FOS, and IGF1R are enriched in the insulin signaling pathway which could contribute to obesity related disorders." (PMID 31013288, 2019). "Several studies have demonstrated cross-talk between HER2 and IGF1R, suggesting that obesity-induced IGF1R signaling may further enhance HER2 activity." (PMID 26709918, 2015). "Because PI3K/Akt, MAPK and IGF-1R activity were all upregulated with obese patient sera exposure, we next explored the effects of obesity-associated factors on nongenomic ERα activity." (PMID 23880059, 2013). "There is a paucity of studies examining the influence of obesity on IGF-1R in tumor tissue." (PMID 21696633, 2011). "Other universal genes previously shown to be increased during the expansion of the β-cell during obesity or pregnancy such as Birc5, Igf1r and Rasgrp1 also failed to increase in PPARγ deficient ob/ob islets (POKO vs. WT) further suggesting an inability of POKO islets to proliferate at a young age." (PMID 22208362, 2011). "We demonstrate that a generalized disruption of IGF1R signalling has a protective action against aging and HFD-induced obesity, specifically by reducing adipose tissue inflammation." (PMID 36353242, 2022). "Especially in obesity-related colorectal carcinogenesis, a relationship between upregulation of the IGF/IGF-1R axis and the accumulation of β-catenin was observed." (PMID 32210144, 2020). "Additionally, we find that malonate is released by the endothelium when IGF-1R levels are reduced, functioning as a WAT modulator with therapeutic potential in the context of obesity and related metabolic complications." (PMID 39747815, 2025). "Further investigations are necessary to elucidate whether the IGF1R pathway is actually inhibited in WAT from HFD middle-aged mice compared to young mice, and how this inhibition might impact age- and obesity-related complications." (PMID 38255206, 2024). "IGF1R plays a modest role in AT formation and function; however, the expression of IGF1R in AT is not changed in obesity." (PMID 38255206, 2024). "Specifically, we have reported that supplementation with both EGCG and BCAA suppresses obesity-related colorectal carcinogenesis in db/db mice by reducing serum levels of insulin and inhibiting activation of the IGF/IGF-1R signaling pathway in the colonic mucosa." (PMID 25789501, 2015). "Several pathophysiological mechanisms of interaction between obesity and CRC have been studied, including insulin resistance, adipocytokine imbalances, alterations in the insulin-like growth factor (IGF)-1/IGF-1 receptor (IGF-1R) axis, chronic inflammation, and oxidative stress." (PMID 28445390, 2017). "Our study found IGF1R and some other IGF family genes significantly correlated with BMI of esophageal cancer patients, indicating the IGF pathway might be played a differential role in tumor progression between obesity and normal body weight esophageal cancer patients." (PMID 32999719, 2020).
leukemia (49 papers, 2010 to 2025). A malignant (clonal) hematologic disorder, involving hematopoietic stem cells and characterized by the presence of primitive or atypical myeloid or lymphoid cells in the bone marrow and the blood. "Distorted IGF-1/IGF-1R signaling has been linked to the development of aggressive and/or refractory leukemia." (PMID 38159164, 2024). "IGF1 is produced in the liver as a growth factor but interestingly, we have found it is also expressed by leukemia-associated myeloid cells, and IGF1R signaling is critical for T-ALL initiation and growth." (PMID 37805579, 2023). "SOMDTP nodes in meta-clades 10 through 15 that are associated with defective IGF1R exist for chemosensitivity mainly to leukemia cell lines." (PMID 33909629, 2021). "In our prior study examining the contribution of IGF1R to leukemia propagation in vivo, we found that a hypomorphic allele of IGF1R (IGF1Rneo) abrogated serial transplantability of mouse T-ALL." (PMID 27532210, 2016). "Additionally, the IGF-1R autocrine loop is an important survival signal in leukemia, and IGF-1R signaling synergistically amplifies Abl receptor tyrosine kinase aberrant forms, one of the most common mutations in leukemia." (PMID 22216158, 2011). "The identification of IGF1R and FGFR1 as novel components of TSLP/CRLF2 signaling enhances our understanding of the molecular mechanisms that underlie TSLP-mediated leukemia proliferation." (PMID 40787610, 2025). "In summary, alterations of InsR and IGF-1r signaling are observed in various leukemia types, which ultimately contribute to the leukemic cell proliferation, evasion of apoptosis, and/or resistance to treatment." (PMID 38159164, 2024). "Consistently, highest levels of IGF1R were found on leukemia cells from mice with BCR-ABL1+ B-ALL and BCR-ABL1+ BA/F3 cells compared to MLL-AF9+ cells." (PMID 39567540, 2024). "Another SNP below suggestive significance, i.e., rs75400242, is located upstream of the Insulin-Like Growth Factor 1 Receptor (IGF1R) gene, which is expressed in human leukemia cells and was previously shown to be associated with AML." (PMID 37509244, 2023). "Altogether, these results indicate that myeloid cells promote T-ALL survival through a combination of close contact with leukemia cells, driven by integrin-mediated interactions and IGF1R activation." (PMID 37805579, 2023). "Using RNA-Seq and RT-qPCR, we demonstrated that NOTCH1 and its respective target genes, such as HES1 and IGF1R, are upregulated and highly activated in MLLr leukemia cells." (PMID 37833915, 2023). "Evaluation of drug sensitivity for compounds targeting leukemia cell lines has prompted the emergence of IGF1R as a potential therapeutic target for the treatment of leukemia." (PMID 33909629, 2021). "The IGF2/IGF1R/NANOG signaling pathway has important functions in leukemia stem cell proliferation, and the knockdown of NANOG induces cell cycle arrest and apoptosis." (PMID 33336042, 2020). "Further support for a crucial role of IGF1R in leukemia was provided by studies showing that IGF1R regulates the cell fate determination of BCR-ABL+ leukemia cells and supports the self-renewal of CML cells." (PMID 29455671, 2018). "These miRNAs contribute to leukemia developments and progression by directly targeting the insulin-like growth factor 1 receptor (IGF1R) and mTOR." (PMID 30110936, 2018). "IGF1R mRNA expression showed a highly significant (P < 0.0001) positive correlation with Nanog mRNA expression in CD34+ leukemia cells." (PMID 30013477, 2018). "High level of IGF1R expression is required for leukemia-initiating cell activity in T-ALL, and inhibition of IGF1R blocks the growth and viability of T-ALL cells." (PMID 30013477, 2018). "More importantly, high levels of IGF1R expression are required for leukemia-initiating cell activity in T-cell acute lymphoblastic leukemia, and inhibition of IGF1R blocks the growth and viability of T-cell acute lymphoblastic leukemia cells." (PMID 30013477, 2018).
leukemia (continued). "IGF1-R inhibitors are a potential therapeutic option in leukemia patients since in vitro IGF1-R inhibition reduced proliferation of leukemic cells." (PMID 26450156, 2015). "Using a normal hematopoietic stem cell line HSC2 as a standard, we found that IRAIN was downregulated in leukemia cell lines as compared with the IGF1R sense coding RNA." (PMID 25092925, 2014). "Ultimately, our results suggest that inhibition of IGF1R-Akt-mTOR signaling plays a key role in the cytotoxic effect of shikonin against U937 leukemia cells." (PMID 23861714, 2013). "The IGF-1R expression of leukemia-initiating cells in T-cell acute lymphoblastic leukemia was maintained by Notch signaling, which also contributed to the maintenance of BCSCs." (PMID 23663564, 2013). "As a multi‐target kinase inhibitor already applied in the treatment of certain leukemias, the antitumor effects of Midostaurin could be enhanced by interacting with IGF1R." (PMID 40152081, 2025). "We then hypothesized that there is differential oncogene- and/or lineage-dependent sensitivity of leukemias to mTORC2 signaling downstream of the IGF1R, which may explain the observed phenotypes of CML, B-ALL and AML in ANXA2 KO mice." (PMID 39567540, 2024). "Interestingly, we have identified the IL-15 production pathway to be activated in leukemia cells cultured in the 3D BM niche-like AML model, with different associated genes upregulated, including EGFR, IGF1R, MET, RELB, and ERBB2." (PMID 37932837, 2023). "IGF1R inhibition yields therapeutic benefits in several solid tumor types and leukemias." (PMID 34394130, 2021). "We found that IGF1R mRNA level was significantly higher in leukemia cells than in normal blood." (PMID 30013477, 2018). "The IGF1-R-associated GEP further underline the biological relevance of IGF1-R in T-ALL pathogenesis as differentially up- and down-regulated genes were enriched for several known players in leukemia such as NOTCH1." (PMID 26450156, 2015). "IGF1R is one of the most abundantly phosphorylated receptor tyrosine kinases in leukemia cells, and phosphorylation is increased in leukemia cells with Ara-C resistance The IGF1R inhibitor BMS-536924 substantially inhibited growth and proliferation of both mouse and human leukemia cells in vitro." (PMID 25092925, 2014). "Recently, two reports demonstrated the essential role of IGF/IGF-1R signaling in the maintenance of leukemia-initiating cells in T-cell acute lymphoblastic leukemia or in the transformation of hematopoietic progenitor cells in the mouse model of acute myelogenous leukemia." (PMID 23663564, 2013). "Therefore, IGF1R directs BCR-ABL+ leukemia cells toward the myeloid fate." (PMID 29455671, 2018). "Thus, we tested IGF1R mRNA levels in several leukemia cell lines." (PMID 30013477, 2018). "However, IGF1R is preferentially phosphorylated in wild type FLT3 leukemia cell lines." (PMID 21552520, 2011). "In addition, HR and/or c-NHEJ deficiency could be induced by the treatment of leukemia/solid tumors with the tyrosine kinase inhibitors (TKi) against the cancer-driven oncogenic tyrosine kinases (e.g., FLT3(ITD), JAK2(V617F), c-KIT(N822K), IGF-1R, EGFR)." (PMID 36497275, 2022). "Notch1 has been shown to directly activate expression of Insulin-like growth factor 1 receptor (IGF1R) in T-ALL, which contributes to leukemia survival through the PI3K/Akt pathway." (PMID 34394130, 2021). "IGF1R plays a role in differentiation of hematopoietic cells and appears to regulate BCR–ABL leukemia cell fate and self-renewal in chronic myeloid leukemia (CML) cells." (PMID 31980503, 2020). "Given the fact that IGF1R is dispensable for the activity of hematopoietic cells but regulates BCR-ABL leukemia cell fate and supports self-renewal of CML cells, targeting IGF1R has been suggested to constitute an ideal anti-leukemia approach." (PMID 29455671, 2018).
leukemia (continued). "To address the mechanisms underlying the dysregulation of IGF1R in leukemia cells, we used a novel R3C method recently developed in our lab, and detected the presence of RNA molecules within the IGF1R promoter and intron 1, where the IGF1R mRNA is not transcribed." (PMID 25092925, 2014). "Remaining candidates (N = 62) comprised BDNF-related genes (SST), MAPK-pathway genes (KRAS, IGF1R, GNG11 and RAP1A), genes related with leukemia (SFRP1) and Rho-Proteins (DHCR7 and RAB21)." (PMID 21569303, 2011). "Our laboratory and others have demonstrated that significant functional cross-talk between AMPK, mTOR, IGF-1R/IRS-1, and Akt signaling factors occur in leukemia cells." (PMID 20863384, 2010). "Moreover, IGF1R, also a NOTCH1 downstream target, is required for leukemia-initiating cell activity in T-ALL." (PMID 37833915, 2023). "IGFBP-2 was identified as the major regulatory carrier in childhood leukemia and exhibited an inverse correlation with IGF-1 levels, suggesting that activation of IGF-1R signaling may confer ALL cells a survival advantage and influence induction of apoptosis." (PMID 20863384, 2010). "TSLP may promote leukemia cell proliferation through several signaling pathways, including JAK-STAT, PI3K/mTOR, and MAPK, as well as through other factors such as RAS, IGF1R, and FGFR1." (PMID 40787610, 2025). "As well, we and others have reported previously that IGF1R is upregulated both transcriptionally and post transcriptionally in T-ALL by NOTCH1, a prominent oncogene in the disease, and that IGF signaling contributes to growth/survival of bulk cells and also to leukemia-initiating activity." (PMID 27532210, 2016).